YAP1 (Yes1 associated transcriptional regulator)
Diseases named in the same sentence as YAP1 in open-access papers (continued):
Sharing a sentence is not in itself a finding about the gene and the disease.
tumor (continued). "We found DUSP10 and YAP1 expression higher in tumor samples than normal tissue, but not of p-p38 in most tumor samples." (PMID 31717606, 2019). "YAP1 upregulates NMU expression and promotes tumor metastasis." (PMID 31575084, 2019). "During long-term surveillance, no tumor was detected, and none of the animals developed neurological signs, indicating that interaction between YAP1 and TEAD proteins is required for tumorigenesis." (PMID 31477715, 2019). "The expression of three genes showed a negative correlation with miR-375 expression and YAP1 re-expression partly abolished the tumor-suppressive effect of miR-375." (PMID 29367737, 2018). "In 75.6% of ccRCC patients YAP1 immunoreactivity was absent in the cytoplasm of tumor cells; however, in 13/54 (24.1%) of ccRCC patients tumor cells exhibited weak to moderate cytoplasmic YAP1 immunoreactivity." (PMID 29850494, 2018). "YAP1 nuclear and cytoplasmic expression levels in the tumor cells did not correlate with demographic and clinical-pathological data of patients with ccRCC." (PMID 29850494, 2018). "The tumor type subgroup analysis demonstrated negative impact of elevated YAP1 on OS in patients with ESCC (HR = 1.85; 95% CI: 1.25-2.73; P = 0.002), GC (HR = 1.41,95% CI: 1.02-1.95; P = 0.037), and CRC (pooled HR = 1.75; 95% CI: 1.42-2.15; P < 0.001)." (PMID 30539010, 2018). "Together, such correlation between miR-363 and YAP1 translocation may confirm the mechanistic involvement of LATS2, as a tumour suppressor in TX-response." (PMID 30046387, 2018). "Additionally, YAP1 and TEAD2, two vital Hippo pathway downstream transcription factors, obviously decreased in IKBKE-silenced tumour cells, suggesting that the reversed EMT process caused by IKBKE downregulation was likely regulated by the Hippo pathway." (PMID 28548934, 2017). "Knocking down YAP1 in H1975, HCC827 or PC9 cells resulted in significant inhibition of cell proliferation, indicating that YAP1 plays a role in the growth of EGFR-mutant tumor cells." (PMID 29163769, 2017). "In summary, our data indicate that fluid force present in the tumour microenvironment can trigger cancer cell motility and metastatic behaviour through modulation of gene expression downstream of ROCK–LIMK–cofilin-activated YAP1 signalling." (PMID 28098159, 2017). "The Hippo pathway consisting of the tumor-suppressing core-kinase cascade (MST and LATS) and oncogenic downstream effector YAP1/TAZ participates in tissue homeostasis, organ size control, and tissue repair and regeneration by regulating tissue-specific stem cells." (PMID 27911857, 2017). "We therefore tested the function of YAP1 directly in a PTC cell line and tumor tissues." (PMID 28036290, 2017). "Furthermore, we stained the intracranial tumours with IKBKE, YAP1, MMP-2, MMP-9, E-cadherin, N-cadherin, β-catenin, vimentin, and snail." (PMID 28548934, 2017). "Expression levels of Lnc BRM together with YAP1 signaling targets are correlated with tumor severity og HCC patients and, therefore, lnc BRM and YAP1 signaling may serve as biomarkers for diagnosis and potential drug targets for HCC." (PMID 28930164, 2017). "This may explain that HCT116 is slightly more sensitive toward ovatodiolide’s treatment; HCT116 also contains a lower intrinsic YAP1 expression level as compared to DLD-1 and demonstrates a lower ability to form tumor spheres as compared to DLD-1." (PMID 28241877, 2017). "YAP1 was weakly expressed or not expressed in non-malignant thyroid tissues, but was highly expressed in the nuclei of tumor specimens, in line with a previous observation." (PMID 28036290, 2017). "YAP1 is an effector of the Hippo pathway, which promoted cell proliferation and tumor growth in mammals, but the influence of YAP1 in GC has not been comprehensively investigated." (PMID 27835600, 2016).
tumor (continued). "To investigate this, we performed biochemical analysis of xenograft lysates, which confirmed RAF1 knockdown and recapitulated the increased expression of YAP1 and GP130 as well as the higher levels of STAT3 phosphorylation observed in the autochthonous tumours." (PMID 28000790, 2016). "To this end, we performed genome-wide analyses to identify YAP1 occupied sites in cancer cell lines representing different YAP1/Hippo pathway tumor etiologies and in non-transformed fibroblasts." (PMID 26295846, 2015). "We hypothesize that miR-375 exerts its tumor suppressive role partly by acting as an upstream regulator of BIRC5 and BCL2L1 through the targeting of YAP1." (PMID 24892549, 2014). "The mRNA expression of YAP1, cyclin E, and DIAP1 during 50–60 days post infection was significantly upregulated suggesting that this period might be important for tumour formation and development." (PMID 24694742, 2014). "The majority of the data published until now detected 11q22 amplification in different tumor types without directly investigating the YAP1 copy alteration." (PMID 24810989, 2014). "The intermediate-cell subtype of cHC-CCs with stem cell features predominantly consisted of tumor cells with intermediate features between hepatocytes and cholangiocytes, which showed no zonal pattern of YAP1 expression." (PMID 24086533, 2013). "While post-treatment YAP1 expression could not be dichotomized due to the limited availability of residual tumor tissue, this did not undermine our primary aim, which was to evaluate the chemotherapy-induced change in YAP1 localization." (PMID 40731926, 2025). "Due to inactivation of Hippo signaling mediators, YAP1 is aberrantly stabilized or activated, which interacts with TEADs, STAT3, and other transcription factors, thereby inducing target genes expressions, and contributing to cancer stem‐like properties, tumorigenesis, and tumor progression." (PMID 39968498, 2025). "Although bioinformatics analysis indicated a positive correlation between the mRNA expression of DCLK1 and YAP1 in tumor samples, there were no significant changes in the mRNA or protein expression levels of YAP1 in PCa cell lines after DCLK1 overexpression or knockdown at the cellular level." (PMID 39781521, 2025). "Moreover, after chemotherapy, high YAP1 staining in this CAF population is associated with reduced CD8+ T cell density, while this is not the case for tumor cells." (PMID 38346978, 2024). "Therefore, YAP1-TEAD complex creates an immunosuppressive microenvironment by stimulating tumor cells to secrete factors that recruit MDSCs, Tregs, and CAFs, which is conducive to the spread and invasion in tumor niche." (PMID 38550587, 2024). "Furthermore, YAP1 and WWTR1 expression inhibits the tumor progression of Merkel cell carcinoma." (PMID 38246995, 2024). "Tumor histological and molecular analysis demonstrated decreased expression of IL-6 and CXCLs and a decreased ratio of MDSCs to CD8+ T cells in the WT CDX simultaneously injected with the YAP1-Sh clones compared with the WT cell-derived tumors in separate mice." (PMID 39630608, 2024). "YAP1/TAZ inhibition may result in reduced migratory capacity without substantially reducing tumor bulk, culminating in disease control but not eradication." (PMID 38477830, 2024). "Similarly, YAP1‐5SA but not YAP1‐WT recovered the greatest tumor burden in Trim65 cKO mice, with a significantly elevated liver weight and liver‐body weight ratio." (PMID 39005234, 2024).
tumor (continued). "In summary, the analysis of RNA-Seq data generated from the mouse YAP1-Sh MB49 cell line and publicly available RNA-Seq data from a human UCB cell line (UC3, GSE186043) led us to hypothesize that YAP1 may play a significant role in tumor immune evasion." (PMID 39630608, 2024). "Additionally, it is unclear whether SOX9 removal directly converts CCA lesions into HCC fate or simply eliminates CCA tumors during tumor formation, thereby allowing HCC to remain in YAP1-independent cHCC-CCA settings." (PMID 39273023, 2024). "Further, we speculate YAP1 antagonism may represent a synergistic strategy to sensitize patients with KRAS-driven LUADs lacking STK11 to anti-PD-1 therapy by promoting a “hot” tumor immune microenvironment." (PMID 37968341, 2024). "Further, our results raise the intriguing possibility that YAP1 antagonism may represent a therapeutic approach to counter anti-PD-1 therapy resistance in STK11-null, KRAS-driven LUADs by modulating tumor-intrinsic gene expression to promote a “hot” tumor immune microenvironment." (PMID 37968341, 2024). "However, the entire Akt-YAP1 Sox9 LKO livers were full of circumscribed tumor foci which were negative or very weak for CK19." (PMID 39273023, 2024). "Interestingly, SOX9-DNMT1 is partially involved only in Akt-NRAS tumor formation but not in Akt-YAP1 tumor development." (PMID 39273023, 2024). "YAP1, a crucial member of the Hippo signaling pathway, and CK19, a marker of LCSCs, were highly expressed in the miR-135b-5p-high group, indicating that the Hippo signaling pathway was dysregulated and the stemness properties of tumor cells were more remarkable." (PMID 36755690, 2023). "In the current study, using TMAs and specimen slides from a relatively large cohort (N = 192) of primary resected SCLC, we assessed the tumor‐derived protein expressions of ASCL1, NEUROD1, POU2F3, YAP1 as well as VIM, a mesenchymal marker which may be a potential assay to define SCLC‐I." (PMID 37789961, 2023). "However, another study showed that ALKBH5 could inhibit tumor cell proliferation and metastasis by directly reducing YTHDFs-dependent YAP1 expression in NSCLC and decreasing YAP1 activity through HuR-dependent control of miR-107/LATS2 expression." (PMID 37007161, 2023). "In support of the hypothesis that CMA acts as a tumor suppressor in the liver, LAMP2A expression was reduced in HCC biopsies compared to their matched adjacent normal tissues, and an anticorrelation with YAP1 and IL6ST could be observed." (PMID 35435804, 2023). "Considering that YAP1 expression in non-collagenous stroma is correlated with tumor stiffness, YAP1 activation might be induced by mesenchymal cellular components, such as fibroblasts, along with matrix stiffness." (PMID 36291755, 2022). "One limitation is that we could not explain why ectopic YAP1 expression suppressed peripheral Ki67+ cell proliferation, while inducing larger fluid-filled tumor volumes than vector controls in severely immunocompromised NOD-SCID mice." (PMID 35930163, 2022). "Inhibition of the Hippo-YAP1 signaling using verteporfin (VP) in combination with transcatheter arterial chemoembolization (TACE), a commonly used therapeutic approach for unresectable HCC, allows reduced tumor burden and improved survival in a transplanted HCC mice model." (PMID 36289774, 2022). "As critical downstream effectors of the Hippo pathway, YAP1 and TAZ lack DNA-binding motifs and thus function through interacting with TEA domain transcription factors (TEADs) to regulate the expression of target genes responsible for tumor cell proliferation and survival." (PMID 36289774, 2022). "Additionally, YAP1 could also form a transactivation complex with AP-1 and ZEB1 to activate predominantly tumor-promoting genes." (PMID 36210463, 2022). "The contribution of YAP1 in tumor immunity has not been clearly established." (PMID 36291755, 2022).
tumor (continued). "As genetic alterations within the Hippo pathway including YAP1 and TAZ are rather rare across tumor types and do not comprehensively identify YAP1/TAZ-driven tumors, target gene signatures have been inferred from genetic interference experiments, transcriptomic and epigenomic analysis." (PMID 35798875, 2022). "Further analysis of the correlation between SAV1 and YAP1 expression in 28 different tissues revealed that in 20 different tissues, the expression of SAV1 and YAP1 was significantly and positively correlated in normal tissues, but the positive correlation was not significant in tumor tissues." (PMID 35864957, 2022). "This means that, even if YAP1 is considered a downstream target gene of miR-375, we could speculate—in line with our findings—that YAP1 signaling in Pheo is hyperactivated by TNKS1 via other, as yet unknown tumor-specific molecular pathways." (PMID 35269556, 2022). "YAP1 and MT1-MMP could cooperate to promote tumor cells invasion and metastasis." (PMID 35350840, 2022). "It is not clear, though, whether there is a sustained interaction of PHD2 with YAP1 in human lung tumors; while such an interaction is highly possible, it might not contribute significantly to tumor growth, because human lung tumors have high levels of YAP1." (PMID 35937460, 2022). "Preclinical and clinical data implicate the transcriptional co-activators YAP1 and its paralog TAZ in resistance to multiple targeted therapies, highlighting the strong need for therapeutic strategies overcoming YAP1/TAZ-mediated resistance across tumor entities." (PMID 35798875, 2022). "Following the treatment of TED-347, which was able to suppress the interaction of TEAD4 and YAP1, the malignant behaviors of cells including proliferation, invasion, and migration were assessed by EDU staining, wound healing, and transwell assay in vitro, while tumor growth was measured." (PMID 33517828, 2021). "Ribo-seq data revealed that UMMD greatly up-regulated the expression of YAP1, interestingly, the up-regulated YAP1 was found to be negatively correlated with the weight of tumor tissues, while no significant change in YAP1 expression was detected by RNA-seq or RT-qPCR assay." (PMID 33996543, 2021). "Increasing CBX4 levels in HCC cells enhances HIF1α-dependent YAP1 nuclear translocation and induces sorafenib resistance, but blocking CBX4 and YAP1 with the CBX4 inhibitor UNC3866 and the YAP1 inhibitor CA3 significantly suppresses tumour cell growth and CSC properties, particularly in SR cells." (PMID 33473171, 2021). "Furthermore, ChIP analysis proved that YAP1/TEAD1 could co-regulate the transcription of HIF1A and further promote tumour glycolysis." (PMID 33218358, 2020). "Moreover, high levels of nuclear YAP1 predicted poor prognosis for patients with a pT2 tumor who did not received additional therapy different from cholecystectomy." (PMID 32218280, 2020). "In LATS1/2; YAP1f/f mice, tumours were negative for YAP1 immunostaining supporting its specificity." (PMID 32404936, 2020). "However, the correlation of YAP1 and the tumor microenvironment in PC is not completely clarified yet." (PMID 33123286, 2020).
tumor (continued). "However, the absence of an association between most of these deletions with YAP1 expression in ERG positive and ERG negative tumour subsets argues against a direct role of YAP1 for the control of genome integrity or double strand breakage repair." (PMID 32488048, 2020). "Of note, although our data showed differences between DDR1b- and DDR2-expressing tumours in YAP1 regulation and other signalling molecules, these may not necessarily reflect differences between DDRs." (PMID 32047176, 2020). "We also show that inhibition of YAP1/TEAD interaction interferes with the expression of AREG, CTGF, CYR61, and MSLN suggesting that YAP1 transcriptional activity may affect the development and persistence of a fibrotic tumor microenvironment." (PMID 32054505, 2020). "Although the functional role of shear stress in tumor growth and metastasis has not been fully clarified, the activation of YAP1 may be considered as a key point for understanding the comprehensive mechanism and identifying novel therapeutic strategies." (PMID 30934860, 2019). "IHC staining of H1299control primary tumours supported these results as NANOG and high levels of nuclear YAP1 are apparent in H1299control tumours, while the active Hippo pathway in H1299RASSF1A tumours retains the majority of YAP1 in the cytoplasm and no NANOG staining is discernable." (PMID 31268606, 2019). "Furthermore, tumor tissues display an elevated YAP1 expression compared to normal tissues due to the amplification of the YAP gene locus." (PMID 29179447, 2017). "The results showed that both GES-1 and YAP1-overexpressing GES-1 cells inoculated into mice could not form tumor, suggesting that the YAP1 gene might not involve in tumorigenesis." (PMID 27835600, 2016). "While YAP1 expression was upregulated by greater than 1.5 fold in Patients 3, 4, 5, and 7, there was not a significant change in YAP1 mRNA levels between non-neoplastic liver and tumor as a cohort." (PMID 27605415, 2016). "In addition, stable knockdown of YAP1 inhibited xenograft tumor growth and lung metastasis, but YAP1 was not related to tumorigenesis in vivo." (PMID 27835600, 2016). "Thus, we can conclude that active Yap1 promotes the self-renewal and tumor initiation of TICs but not NTCs." (PMID 26695440, 2016). "These evidences suggest that YAP1 expression is not a direct factor affecting tumor formation, but that YAP1 over-expression could accelerate tumor cell growth." (PMID 27835600, 2016). "Thus, tumours with low RAF1, high YAP1 expression contain larger clusters of nuclear STAT3." (PMID 28000790, 2016). "Moreover, by directly targeting Hippo signalling effector YAP1, gga-miR-375 may directly or indirectly affect cyclin E and DIAP1 during the early stages of ALV-J infection, resulting in a range of effects on tumour development." (PMID 24694742, 2014). "Thus, it is not clear if YAP1-positive SCLC tumours represent a distinct subtype." (PMID 37870696, 2023). "However, in the absence of these phosphorylation events, YAP1 can translocate into the nucleus and partner with different transcription factors and contribute to multiple gene expression events, resulting in cell proliferation and tumor growth." (PMID 35937460, 2022). "Finally, to determine whether there might be a relationship between HES1, YAP1, and CDKN1C in human tumor tissue, we examined their expression at the transcript and protein level (when available) in human RMS tumor samples by querying published databases generated for the RMS research community." (PMID 36037042, 2022). "It is not clear whether YAP1 is a key factor in tumor metastasis and DC infiltration." (PMID 34150844, 2021). "The survival of tumor cells in this model in the absence of Kras is mediated by the upregulation of the transcriptional coactivator Yap1, a downstream mediator of the Hippo signaling cascade, and Tead2, forming Yap1/Tead2 complexes coordinating downstream gene expression." (PMID 34888306, 2021).